NAMPT (nicotinamide phosphoribosyltransferase)
Diseases named in the same sentence as NAMPT in open-access papers (continued):
Sharing a sentence is not in itself a finding about the gene and the disease.
metastatic tumors (3 papers, 2015 to 2021). "Elevated expression of NAMPT is associated with more advanced tumor stage and metastatic disease." (PMID 25946974, 2015). "The levels of NAMPT are high in many tumor types, and the percentage of tumors with high NAMPT levels with increases in late-stage and metastatic tumors is also high." (PMID 33384409, 2021). "Moreover, it shows that NAMPT is upregulated in patients with more advanced tumor stage and metastatic disease which may prove to be clinically relevant." (PMID 25946974, 2015).
neuroblastoma (3 papers, 2022 to 2023). Neuroblastoma (NB) is the most common solid, extracranial childhood tumor. "NAMPT is a valid therapeutic target as inhibition promoted neuroblastoma cell death in vitro and prevented tumor growth in vivo." (PMID 35814452, 2022). "Neuroblastoma cell lines were assessed for basal expression of N-MYC, NAMPT, as well as nicotinate phosphoribosyltransferase (NAPRT)." (PMID 35814452, 2022).
osteonecrosis (3 papers, 2022 to 2025). A none disease characterized by death of bone tissue due to a lack of blood supply. "The aim of this study was to investigate the potential role of serum nicotinamide phosphoribosyltransferase (NAMPT) in non-traumatic osteonecrosis of femoral head (NONFH)." (PMID 36443772, 2022).
ovarian tumors (3 papers, 2021 to 2023). "NAMPT inhibition suppresses the senescence-associated CSC increase and resistance induced by cisplatin in ovarian tumors." (PMID 33384409, 2021).
pancreatic adenocarcinoma (3 papers, 2015 to 2023). "For example, pancreatic adenocarcinoma cells are more susceptible to the tumor-specific, PARP-independent metabolic catastrophe and cell death caused by β-lapachone when NAMPT is inhibited." (PMID 36899911, 2023).
pancreatic neuroendocrine tumor (3 papers, 2019 to 2023). Pancreatic endocrine tumor, also known as pancreatic neuroendocrine tumor (PNET), describes a group of endocrine tumors originating in the pancreas that are usually indolent and benign, but may have the potential to be malignant. "Recently KPT-9274, an inhibitor of nicotinamide phosphoribosyltransferase (NAMPT) and p21-activated kinase 4 (PAK4), was found active in pancreatic neuroendocrine tumors and is currently being evaluated in a human phase 1 study in patients with advanced solid malignancies." (PMID 37894327, 2023).
pneumonia (3 papers, 2021 to 2026). An acute, acute and chronic, or chronic inflammation focally or diffusely affecting the lung parenchyma, caused by an infection in one or both of the lungs (by bacteria, viruses, fungi, or mycoplasma.). "Our computational-experimental pipeline prioritizes four biomarkers (NAMPT, NFKBIA, SLC40A1, PRKCQ) that stratify pneumonia risk and predict targeted drugs for therapeutic repurposing." (PMID 41557688, 2026). "Transcriptional profiling confirmed marked dysregulation of all four model genes (NAMPT, NFKBIA, SLC40A1, PRKCQ) in pneumonia cases versus controls (p < 0.001)." (PMID 41557688, 2026).
thyroid (3 papers, 2014 to 2018). "This is the first study demonstrating NAMPT overexpression in thyroid malignancies using quantitative RT-PCR." (PMID 25946974, 2015). "In this study, we analyzed NAMPT expression in 40 malignant and in 67 benign thyroid tissue samples using qPCR." (PMID 25946974, 2015). "Reported alteration of NAMPT expression might suggest its involvement in thyroid pathologies." (PMID 29546048, 2018). "Reported alteration of NAMPT expressions might suggest its involvement in thyroid pathologies." (PMID 29546048, 2018). "Despite the fact that NAMPT is involved in maintaining cell energy balance, its overexpression in hyperfunctioning Graves' thyroids has not been observed." (PMID 29546048, 2018).
type 1 diabetes (3 papers, 2019 to 2024). "In this study, we investigated whether partially disrupting NAMPT-mediated NAD+ biosynthesis or deleting SIRT3/SIRT5 would accelerate early neuroretinal dysfunction in the STZ-induced mouse model of type 1 diabetes." (PMID 30846716, 2019). "Therefore, the motivation behind this study was to test whether there was a neuroprotective role for metabolic regulation via NAMPT-mediated NAD+ biosynthesis, SIRT3, or SIRT5 in a mouse model of type 1 diabetes." (PMID 30846716, 2019).
ulcerative colitis (3 papers, 2016 to 2024). An inflammatory bowel disease involving the mucosal surface of the large intestine and rectum. "In particular, nicotinamide phosphoribosyltransferase (R = 0.515, p = 0.020) and hyaluronan synthase 1 (R = 0.531, p = 0.016) exerted significant correlations with the presence of ulcerative colitis." (PMID 38256678, 2024). "However, the role of (e) NAMPT in inflammatory macrophages in ulcerative colitis is insufficiently understood." (PMID 36552583, 2022).
acute coronary syndrome (2 papers, 2022 to 2023). Signs and symptoms related to acute ischemia of the myocardium secondary to coronary artery disease. "For example, the increased expression of visfatin in acute coronary syndrome patients might exert a protective effect by the upregulation of the NAMPT/NAD+/Sirt1 signaling pathway." (PMID 36128447, 2022).
asthma (2 papers, 2020 to 2024). "This hypothesis is further complemented by the M2 polarization profile (APOE, TXN, TGM2, STING1, NAMPT) enriched in this group, a dominant macrophage profile in high Th2-type asthma in humans and one known to activate the Th2 response with downstream eosinophilic infiltration and airway remodeling." (PMID 39594673, 2024). "They include RBM42, STX5, and TRIM41 in asthma, CYP27A1, GM2A, LGALS9, SPI1, and NLRC4 in COPD, as well as ATF3, PPP1R15A, ZFP36, SOCS3, NAMPT, and GADD45B in IPF." (PMID 31952466, 2020). "These genes included RBM42, STX5, and TRIM41 in asthma, CYP27A1, GM2A, LGALS9, SPI1, and NLRC4 in COPD, ATF3, PPP1R15A, ZFP36, SOCS3, NAMPT, and GADD45B in IPF, LRRC48 and CETN2 in asthma-COPD, COL15A1, GIMAP6, and JAM2 in asthma-IPF and LMO7, TSPAN13, LAMA3, and ANXA3 in COPD-IPF." (PMID 31952466, 2020).
brain cancer (2 papers, 2019 to 2024). A primary or metastatic malignant neoplasm affecting the brain. "Recently, it was shown that NAMPT inhibitors lead to vulnerability in IDH1 mutated brain cancer cells." (PMID 31888244, 2019). "To investigate howU87MG expressed NAMPT within other known brain cancer cell lines,we plotted the NAMPT mRNA levels of a large compendium of 25 braincancer cell lines retrieved from the Human Protein Atlas." (PMID 38924492, 2024).
Burkitt lymphoma (2 papers, 2022 to 2023). A rare form of malignant mature B-cell non-Hodgkin lymphoma. "Taken together, our in vivo data indicate that the new NAMPT inhibitors delayed and/or prevented tumor growth in a mouse Burkitt lymphoma model, with JJ08 being the most potent anticancer agent." (PMID 36838885, 2023). "The promising results presented above led us to explore the potential therapeutic efficacy of the new NAMPT inhibitors in a mouse xenograft model of Burkitt lymphoma." (PMID 36838885, 2023). "Finally, in vivo administration of the new NAMPT inhibitors in a mouse xenograft model of human Burkitt lymphoma delays tumor growth and significantly prolongs mouse survival." (PMID 36838885, 2023). "Importantly, in vivo administration of the new NAMPT inhibitors as a single agent prevented and/or delayed tumor growth in an animal model of human Burkitt lymphoma and significantly prolonged median survival, thereby underlining the therapeutic potential of these molecules." (PMID 36838885, 2023).
cholangiocarcinoma (2 papers, 2023 to 2025). A carcinoma that arises from the intrahepatic biliary tree (intrahepatic cholangiocarcinoma) or from the junction, or adjacent to the junction, of the right and left hepatic ducts (hilar cholangiocarcinoma). "Canagliflozin inhibits cholangiocarcinoma cell growth and migration and its anti-tumor effect is enhanced when combined with an NAMPT inhibitor." (PMID 39940750, 2025). "Canagliflozin treatment upregulated nicotinamide phosphoribosyltransferase (NAMPT), NAD+, and sirtuin 1 in cholangiocarcinoma and activated the NAD+ salvage pathway." (PMID 39940750, 2025).
chorioamnionitis (2 papers, 2015 to 2023). A morphologic finding indicating inflammation of the fetal sac membranes. "We revealed and verified significant change in levels of lipocalin-1, glycodelin, and nicotinamide phosphoribosyltransferase due to the presence of microbial invasion of the amniotic cavity and histological chorioamnionitis." (PMID 26120581, 2015). "Prior analyses of amniotic fluid cell-free RNA transcriptomes from women with preterm births demonstrated prominent NAMPT dysregulation with eNAMPT levels in amniotic fluids reflecting the presence of IAI/chorioamnionitis." (PMID 37415908, 2023). "Supporting the focus on eNAMPT as an IAI/IUI target was the observation that women with chorioamnionitis showed dramatic placental NAMPT expression, compared to non-chorioamnionitis women." (PMID 37415908, 2023).
Cognitive impairment (2 papers, 2018 to 2025). Abnormal cognition is characterized by deficits in thinking, reasoning, or remembering. "In the current study, we show that neuronal C/EBPβ elicits neuronal senescence and triggers cognitive deficits and motor impairments via inactivating NAMPT, which is cleaved by active AEP, shortening the lifespan." (PMID 40308001, 2025). "Consistently, administration of NMN or #11a that blocks NAMPT proteolytic fragmentation substantially increases NAD+ concentrations and elongates the life expectancy of Thy 1‐C/EBPβ Tg/Tg mice, accompanied by amelioration of cognitive deficits." (PMID 40308001, 2025).
diabetic cardiomyopathy (2 papers, 2023 to 2024). Diabetic cardiomyopathy is a disorder of the heart muscle in people with diabetes. "A recent research has shown that NAMPT enhances antioxidant defence in diabetic cardiomyopathy through the NADPH‐dependent reduction system." (PMID 39535387, 2024).
esophageal cancer (2 papers, 2022 to 2025). A primary or metastatic malignant neoplasm involving the esophagus. "NAMPT inhibitors have demonstrated antitumor activity in certain cancer cells, but it is not known whether they can achieve the same effect in esophageal cancer." (PMID 36432602, 2022).
gestational diabetes (2 papers, 2019 to 2024). Carbohydrate intolerance first diagnosed during pregnancy. "EGR1 and NAMPT can be used as marker genes for childhood-onset T2D, and gestational diabetes and chronic inflammation are risk factors that lead to the development of childhood-onset T2D." (PMID 30755828, 2019). "Because NAMPT is also conspicuously up-regulated in children with T2D, it is necessary to further study the genetic mechanism of NAMPT in gestational diabetes patients and their offspring." (PMID 30755828, 2019). "Interestingly, the expression of NAMPT was found to be significantly higher in patients with gestational diabetes." (PMID 30755828, 2019). "This indicates that NAMPT is involved in the molecular mechanism of gestational diabetes." (PMID 30755828, 2019). "Thus, there is a genetic mechanism of NAMPT in gestational diabetes patients and their offspring." (PMID 30755828, 2019).
Graves ophthalmopathy (2 papers, 2016 to 2018). An autoimmune disorder of the EYE, occurring in patients with Graves disease. "We have previously reported NAMPT overexpression in leukocytes of Graves' orbitopathy patients and its correlation with TSH receptor autoantibodies (TRAb) levels." (PMID 29546048, 2018). "We suggested that upregulation of NAMPT in leukocytes might reflect its potential immunological properties in patients with Graves' orbitopathy." (PMID 29546048, 2018).
Impaired glucose tolerance (2 papers, 2023 to 2024). An abnormal resistance to glucose, i.e., a reduction in the ability to maintain glucose levels in the blood stream within normal limits following oral or intravenous administration of glucose. "Similarly, NMN treatment reversed the significant decline in NAD+ levels and impaired glucose tolerance observed in female, but not male, NAMPT-heterozygous mice." (PMID 38921475, 2024).
kidney cancer (2 papers, 2023 to 2025). Primary or metastatic malignant neoplasm involving the kidney. "The overexpression of visfatin or nicotinamide phosphoribosyltransferase (NAMPT) was revealed in the tumor tissues of patients with breast, pancreas or kidney cancers; they are associated with enhanced cancer cell growth, migration and invasion and the stimulation of angiogenesis." (PMID 37298551, 2023).
lipid metabolic disorders (2 papers, 2025 to 2026). "Inhibition of NAMPT reversed the protective effects of METTL1-deficient MSCs against MASLD-related lipid metabolic disorders." (PMID 41903937, 2026). "This study provides convincing evidence that JHP may partially ameliorate early NONFH by restoring the balance of lipid metabolism disorder and reversing pathological events during early NONFH progression by regulating the NAMPT/STK11/HMGCR/ACAT1 axis." (PMID 40988117, 2025).
lung diseases (2 papers, 2022 to 2024). "Given the complex role of NAMPT in pulmonary disorders, whether NAMPT is involved in some pathophysiologic processes in other cell populations needs to be clarified in future studies." (PMID 35012648, 2022).
lupus nephritis (2 papers, 2023 to 2024). Glomerulonephritis in the context of systemic lupus erythematosus. "A recent study has identified nicotinamide phosphoribosyltransferase (NAMPT), which facilitates the biosynthesis of nicotinamide adenine dinucleotide (NAD+), as a metabolic checkpoint of CD4+ T cells in lupus nephritis for its prominent pro-inflammatory." (PMID 39737193, 2024).
Neonatal sepsis (2 papers, 2019 to 2020). Systemic inflammatory response to infection in newborn babies. "A previous study indicated that NAMPT expression was elevated in neonatal sepsis, and was associated with inflammatory responses, suggesting that NAMPT was a vital regulator in inflammatory reactions." (PMID 32618342, 2020). "Then, we analyzed the relationship between miR-96-5p and NAMPT, and the data indicated that the expression of miR-96-5p was negatively correlated with NAMPT in neonatal sepsis." (PMID 32618342, 2020). "The expression levels of miR-96-5p and NAMPT were first detected in neonatal sepsis and control serum by qRT-PCR, and the result shown that miR-96-5p level was significantly decreased in the serum of neonatal sepsis compared with the control." (PMID 32618342, 2020). "In addition, the NAMPT protein level was detected using Western blot, and the result showed that NAMPT expression was increased in neonatal sepsis, which was consistent with the qRT-PCR result." (PMID 32618342, 2020). "In the present study, we first demonstrated that miR-96-5p participated in inflammatory responses through suppressing its target gene NAMPT and NF-κB pathway in neonatal sepsis, which may provide a theoretical basis for research on diagnosis and treatment of neonatal sepsis." (PMID 32618342, 2020).
neuroendocrine carcinoma (2 papers, 2023 to 2025). A malignant neuroendocrine neoplasm composed of cells containing secretory granules that stain positive for NSE and chromogranin. "Our findings provide a rationale for simultaneous targeting of NAR metabolism and NAMPT therapeutically in neuroendocrine carcinoma." (PMID 38092728, 2023). "We found that SCLC and other neuroendocrine carcinomas (NECs) were vulnerable to NAMPT inhibition." (PMID 38092728, 2023). "Depleting blood NAR through nutritional or genetic manipulations was synthetically lethal to tumors when combined with NAMPT inhibitors, suggesting a rationale for simultaneously targeting NAR metabolism and NAMPT as a therapeutic strategy in neuroendocrine carcinoma." (PMID 40775221, 2025).
papillary thyroid cancers (2 papers, 2015 to 2018). "When papillary thyroid cancers (n = 29) were analyzed separately, NAMPT expression was also found to be higher than in the control group (P = 0.0002)." (PMID 25946974, 2015).
periodontal disease (2 papers, 2014 to 2025). "In this study, we aim to investigate the increased vascular permeability associated with periodontal disease, with a particular focus on abnormal lipid metabolism due to NAMPT." (PMID 40303304, 2025).
psoriasis vulgaris (2 papers, 2023 to 2025). Plaque psoriasis is the most common presentation of psoriasis. "We identified three autophagy-related genes (BIRC5, NAMPT and BCL2) with high diagnostic value for the early diagnosis of psoriasis vulgaris through bioinformatics analysis and clinical samples." (PMID 38129460, 2023). "In the GSE6710 dataset, BIRC5, NAMPT, and BCL2 had high diagnostic values in both mild and moderate-severe psoriasis vulgaris samples." (PMID 38129460, 2023). "The expression levels of BIRC5, NAMPT, and BCL2 were tested by ELISA in the blood samples of patients with psoriasis vulgaris and healthy controls." (PMID 38129460, 2023). "Therefore, we considered three genes (BIRC5, NAMPT, and BCL2) as potential biomarkers for the early diagnosis of psoriasis vulgaris." (PMID 38129460, 2023). "Therefore, we hypothesized BIRC5, NAMPT, and BCL2 as potential biomarkers for the early diagnosis of psoriasis vulgaris using bioinformatics analysis and clinical samples." (PMID 38129460, 2023). "Therefore, we hypothesized that BIRC5, NAMPT, and BCL2 might serve as biomarkers for the early diagnosis of psoriasis vulgaris." (PMID 38129460, 2023). "Therefore, we proposed that BIRC5, NAMPT and BCL2 may be as potential biomarkers for the early diagnosis of psoriasis vulgaris." (PMID 38129460, 2023).
sarcoidosis (2 papers, 2022 to 2024). Sarcoidosis is a multisystemic disorder of unknown cause characterized by the formation of immune granulomas in involved organs. "Genomic studies corroborated HBEGF and NAMPT among the top dysregulated genes and identified cytokine-related and fibrotic pathways in lung granulomatous tissues from sarcoidosis." (PMID 36388923, 2022). "Finally, NAMPT expression in sarcoidosis lymph node (p = 0.0009) and lung tissues (p = 0.005) was significantly higher compared to healthy tissue." (PMID 36388923, 2022). "Elevated expression of NAMPT, HBEGF, and ANG-2 was noted in lung and lymph node tissues from individuals with sarcoidosis." (PMID 38611622, 2024). "Quantification of biomarker tissue expression by IHC was largely concordant with plasma biomarker results, with elevated expression of NAMPT, HBEGF, and ANG-2 in lung and lymph node tissues from subjects with sarcoidosis." (PMID 36388923, 2022).
sarcoma (2 papers, 2020 to 2023). A usually aggressive malignant neoplasm of the soft tissue or bone. "The study supported that nicotinamide-derived molecules could be differently expressed in tumors and that NAMPT was overexpressed in certain sarcomas which could correlate with tumor behavior." (PMID 32752274, 2020).
Waldenstrom macroglobulinemia (2 papers, 2019 to 2021). "Furthermore, based on the data supporting crosstalk between oncogenic signaling and NAMPT, co-targeting NAMPT along with other signaling pathway molecules, as has been described with the BTK inhibitor ibrutinib in Waldenstrom macroglobulinemia cells, could be a promising therapeutic strategy." (PMID 32010616, 2019).
acute lymphoblastic leukemia (1 paper, 2017). Leukemia with an acute onset, characterized by the presence of lymphoblasts in the bone marrow and the peripheral blood. "A recent work showed that STF-118804, a new highly specific NAMPT inhibitor, had promising results in in vivo and in vitro preclinical models of high-risk acute lymphoblastic leukemia." (PMID 29156703, 2017).